EGFR (epidermal growth factor receptor)
Diseases named in the same sentence as EGFR in open-access papers (continued):
Sharing a sentence is not in itself a finding about the gene and the disease.
cancer (continued). "Epidermal growth factor (EGF) and its receptor (EGFR) as well as the EGFR-coupled Ras > Raf > MEK > ERK pathway are known to affect the survival of cancer cells upon therapeutic treatment." (PMID 20428086, 2010). "This compound attenuates PDGFRβ and VEGFR2 signalling in cells in a TCPTP-dependent manner and functions as a negative regulator of EGFR phosphorylation in cancer cells." (PMID 20055993, 2010). "The majority of human epithelial cancers are marked by the activation of EGFR, and it was the first growth factor receptor to be proposed as a target for cancer therapy." (PMID 20828404, 2010). "One of the potential prognostic factors is the epidermal growth factor receptor (EGFR), which has been identified as an important prognostic marker in several other cancer types." (PMID 20502457, 2010). "Since our results with spermidine implied that it can function as a TC45 activator in mouse cells, we tested if spermidine would have an effect on EGFR phosphorylation in human cancer (HeLa) cells." (PMID 20055993, 2010). "In summary, our findings indicate that 1, 9 PA can sensitize cancer cells to cetuximab-mediated anti-EGFR therapy by downregulating HIF-1α and can enhance cellular response to cetuximab treatment in cancer cells bearing oncogenic Ras mutations." (PMID 21209911, 2010). "Elevated levels of the epidermal growth factor receptor (EGFR), a growth-factor-receptor tyrosine kinase, has been identified as a common component of multiple cancer types and appear to promote growth of tumors." (PMID 27713315, 2010). "New therapies using the rationale that cancer cells express or amplify certain signaling proteins, such as the epidermal growth factor receptor (EGFR) family of tyrosine kinase receptors, are under investigation." (PMID 20579378, 2010). "Increased EGFR expression has been observed in many experimental cancer cell lines and human tumors, including NSCLC, and it has been associated with advanced tumor stage, metastasis, and poor prognosis." (PMID 20731837, 2010). "Over the past two decades, novel cancer therapies targeting EGFR have been developed and extensively studied." (PMID 21209911, 2010). "Epidermal growth factor receptor (EGFR) has been regarded as an attractive target molecule for the treatment of various cancers including NSCLC." (PMID 20731837, 2010). "We previously reported that cetuximab can markedly downregulate the high basal levels of hypoxia-inducible factor-1 alpha (HIF-1α) by inhibiting HIF-1α protein synthesis in cancer cell lines that are sensitive to EGFR inhibition." (PMID 21209911, 2010). "There has recently been heightened interest in the relevance of several biomarkers for the selection of patients who will benefit from EGFR-targeted therapies for the treatment of CRC and other EGFR-associated cancers." (PMID 20680106, 2010). "Several monoclonal antibodies or small molecule inhibitors directed against EGFR have been successfully used in cancer therapy." (PMID 20540809, 2010). "The epidermal growth factor receptor (EGFR) family was the first growth factor receptor to be identified in cancer cells." (PMID 20184722, 2010). "Expression of EGFR and HER2 is associated with aggressive cancers and inhibitors of EGFR-HER signaling are tested in clinical trials." (PMID 21029421, 2010). "Other reports also document the importance of cotargeting downstream molecules, including the Hsp90 regulated effectors PI3K/mTOR and MEK, in regaining drug responsiveness in EGFR mutant cancers." (PMID 20628489, 2010). "The expression levels of EGFR have been correlated with the pathogenesis of a broad range of human cancers." (PMID 20540809, 2010).
cancer (continued). "Targeted cancer therapy by RNA interference (RNAi) is a relatively new approach, and silencing EGFR by RNAi has already shown promising results." (PMID 20064265, 2010). "The role of EGFR in oncogenesis is widely accepted, as activation of the receptor is known to result in important cancer hallmarks such as proliferation and resistance to apoptosis." (PMID 20502457, 2010). "Increased levels of EGFR gene expression are observed in many cancers, including NSCLC, and its expression is correlated with an adverse prognosis." (PMID 20459863, 2010). "Two kinase inhibitors in clinical trails for several different cancer types are gefitinib (targets EGFR) and vandetinib (antagonist of VEGFR, EGFR and RET-tyrosine kinase)." (PMID 20718987, 2010). "The oncogenic nature of RTKs, addiction of cancers to growth signals and given the clustering of c-CBL, EGFR and MET mutations, it is possible that the transforming effect of c-CBL mutations is most likely a combinatorial effect of the three." (PMID 20126411, 2010). "EGFR is almost universally expressed in H and N cancers, and high levels of expression have been correlated with poor outcome." (PMID 21274259, 2010). "This review summarizes recent studies on the crosstalk between Wnt and EGFR signaling in cancers and points out several possible convergence points." (PMID 20828404, 2010). "This discrepancy between the EGFR gene copy number and the immunohistochemical detection of the protein has been reported before in several cancers, and has been attributed to a post-transcriptional phenomenon mediated at the mRNA level." (PMID 20664595, 2010). "Expression of proteins in the human epidermal growth factor receptor (EGFR) pathway has been reported as a prognostic marker in several types of cancer." (PMID 20502457, 2010). "In contrast, overexpression of HIF-1α in cancer cells that were originally sensitive to the treatment conferred substantial resistance to anti-EGFR therapy." (PMID 21209911, 2010). "Epidermal growth factor receptor ligands have been studied in several cancers as potential biomarkers for EGFR-targeted therapy; however, the results have been mixed depending on organ sites and clinical specimens used for testing." (PMID 20856931, 2010). "Mutation and dysregulation of epidermal growth factor receptor (EGFR) family members are related to cancer onset and progression." (PMID 20462431, 2010). "We previously showed that cetuximab downregulates HIF-1α in cancer cells sensitive to anti-EGFR therapy through inhibition of HIF-1α protein synthesis, which was prevented by expression of a myristoylated Akt that is constitutively active." (PMID 21209911, 2010). "Our results showed that TN-C was involved in the PAR1-mediated EGFR transactivation in cancer cells for the first time." (PMID 20723226, 2010). "It follows that deletion of genes encoding for both thymidine kinase and VGF leads to further selectivity of vaccinia virus in cancers with an activated EGFR-Ras pathway." (PMID 20543907, 2010). "Comparison of ALK fusion status with results characterizing the presence of EGFR and KRAS mutations in the same set of cancer samples revealed that ALK fusions occurred in the absence of KRAS mutations." (PMID 20624322, 2010). "The low number of amplified cases we found is in line with data reported in the recent literature showing that EGFR gene is rarely amplified in human cancers." (PMID 20843314, 2010). "In recent years a considerable body of evidence shows that Wnt and EGFR crosstalk with each other in cancer development." (PMID 20828404, 2010). "Erlotinib hydrochloride belongs to a group of anti cancer drugs known as inhibitors of epidermal growth factor receptor (EGFR) tyrosine kinase which is highly expressed in different forms of cancers." (PMID 22615615, 2010).
cancer (continued). "The targeted toxins bind to a surface antigen or receptor overexpressed in cancer, such as the epidermal growth factor receptor, transferrin receptor, interleukin-13 or interleukin-4 receptor." (PMID 22069569, 2010). "The crystal structures of its tyrosine kinase domain (EGFR-TK) complexed with small molecule inhibitors revealed the kinase inhibition modes, prompting us to search for novel anti-cancer drugs." (PMID 20657425, 2010). "The downstream effects of inhibition in EGFR-dependent cancer cells include decreased TGF-α secretion, angiogenesis, cell migration, invasion, and induction of apoptosis." (PMID 20037743, 2010). "We compiled a reliable list of L/R pairs associated with PTC and validated the biological role of one of the emerged L/R pair, the TGFA/EGFR, in this cancer, in vitro." (PMID 20877637, 2010). "If clinical studies of cancer patients treated with an EGFR inhibitor are analysed, one finds clear reports of therapy induced abdominal, chest and generalized pain." (PMID 21187008, 2010). "ERRFI1 acts as a negative regulator of EGFR and the ERbB family, while dysregulation of TACC (transforming acidic coiled coil) genes, components of the centrosome, has been implicated in cancer development." (PMID 21304175, 2010). "Our previous studies have demonstrated that the combination of lovastatin and EGFR-TKI have resulted in synergistic cytotoxicity in a variety of human cancer derived cell lines." (PMID 20838437, 2010). "In many cancers, excessive EGFR overexpression has been shown to stimulate angiogenesis, cell survival, and metastatic proliferation." (PMID 20509969, 2010). "We have analyzed three differently selected populations of H and N cancer in order to further understand the incidence and potential predictive ability of a subset of specific anti-EGFR candidate biomarkers." (PMID 21274259, 2010). "Continuing these studies in ovarian and other types of cancers will increase our likelihood of achieving success in targeting EGFR-dependent tumors." (PMID 20037743, 2010). "These pathways, which include RAS–MAPK signalling, have been extensively studied in HNSCC, and seem to have a critical role in the survival and proliferation of cancer cells and EGFR is overexpressed in more than 50% of HSCC specimens." (PMID 20700123, 2010). "Decorin is a functional component of the ECM, and is also considered to be a novel biological ligand for EGFR, which is frequently expressed at elevated levels in multiple cancers of epithelial origin." (PMID 20092659, 2010). "EGFR has emerged as one of the novel receptors expressed on the surface of a variety of cancers such as colorectal, head and neck, and lung malignancies." (PMID 20509969, 2010). "E1B 19K-deleted Ad5-infected cancer cells also expressed lower levels of EGFR and anti-apoptotic proteins." (PMID 20543907, 2010). "EGFR signaling plays critical roles in the genesis of adenomas and maintenance of carcinomas during intestinal tumorigenesis." (PMID 20828404, 2010). "A-982605 is selective at inhibiting IGF1R and effective as a single agent or in combination with clinically approved agents targeting EGFR in several cancer models in vivo." (PMID 19732452, 2009). "Similar to our findings for EGFR, the IGFBP3 regions associated with modified risk appear to be functionally important in cancer." (PMID 19603096, 2009). "Other areas of anti-EGFR therapythat should be investigated include the ability of the various anti-EGFRtherapeutic modalities to sensitize cancer cells to other forms of chemotherapyoriginally considered refractory for anindividual patient." (PMID 19390622, 2009).
cancer (continued). "Among them, EGFR and VEGFR-2 pathways, important in cancer cells and cancer-associated endothelial cells, respectively, are the most extensively studied." (PMID 19390592, 2009). "Further development of EGFR inhibitors for esophageal and GEJ cancers should be driven by better understanding of EGFR pathway disregulation that drives cancer progression in a sensitive patient population." (PMID 19636422, 2009). "Overexpression of EGFR and its ligands, were reported for various epithelial tumors in the 1980s and generated interest in EGFR as a potential target for cancer therapy." (PMID 19723324, 2009). "Previous studies have shown EGFR overexpression in the advanced stage, poor prognosis and metastatic human cancer." (PMID 19747398, 2009). "Presumably, these cancers are driven by the activation of other signalling molecules beyond the EGFR." (PMID 19240716, 2009). "This review clearly shows the impact of anti-EGFR therapy on cancer treatment since improved treatment results can be seen with the use of anti-EGFR therapy in many common cancers." (PMID 19750187, 2009). "Growth receptor signaling via IGF1R and EGFR has been known to induce cell survival and proliferation in cancer cells via activation of the PI3Kinase and Akt pathway." (PMID 19323821, 2009). "TKIs result primarily in G1 cell arrest in cancer cell lines with wild type EGFR, versus induction of apoptosis in cell lines with mutant EGFR." (PMID 19159467, 2009). "Targeting EGFR with monoclonal antibodies or tyrosine kinase inhibitors has improved treatment strategies against cancer during the past few years." (PMID 19127259, 2009). "Although many of these ligands are upregulated in cancers, very little is known about their effect on EGFR trafficking." (PMID 19531065, 2009). "This uses a combination of ER, HER2, CK5 and EGFR to generate four groups, which in this study gives a frequency of basal-like cancers in this cohort similar to that described earlier." (PMID 19165203, 2009). "We now evidence de novo expression of two ligands of EGFR in dysplasia that are frequently over expressed in cancers." (PMID 19529782, 2009). "Both monoclonal antibody against EGFR and/or tyrosine kinase inhibitors are now in use clinically for treatment of advanced cancer." (PMID 19750187, 2009). "Our results also were identical with previous studies showing higher expression of membranous EGFR frequently was detected and had a poorer survival outcome in many cancer cells." (PMID 19747398, 2009). "Ongoing and future research will expand the applications ofanti-EGFR therapy, elucidate optimal combinations and sequences, discoverpathways of resistance, and continue to benefit cancer patients." (PMID 19424511, 2009). "Epidermal growth factor receptor (EGFR) is frequently overexpressed in a large number of cancers, including breast, lung, prostate, head and neck, and colon, and is a biomarker of the poor prognosis of many of these diseases." (PMID 19416474, 2009). "We present a large-scale computational investigation of activation mechanisms in the ABL and EGFR kinase domains by a panel of clinically important cancer mutants ABL-T315I, ABL-L387M, EGFR-T790M, and EGFR-L858R." (PMID 19714203, 2009). "In the past two decades we have seen the successful development of EGFR-targeted drugs, expanding treatment options for cancer patients." (PMID 19654571, 2009). "One of these cancers is colorectal cancer and the approval of anti-EGFR monoclonal antibodies in the treatment of metastatic colorectal cancer has expanded the armamentarium against this disease." (PMID 19750187, 2009). "EGFR has been detected in the nuclei of cancer cells and in primary tumor specimens of various origins, as well as in those of other highly proliferative tissues." (PMID 19529774, 2009). "Collectively, the results of this study have revealed thermodynamic and mechanistic catalysts of kinase activation by major cancer-causing mutations in the ABL and EGFR kinase domains." (PMID 19714203, 2009).
cancer (continued). "Epidermal growth factor receptor (EGFR) inhibitors have shown only modest clinical activity when used as single agents to treat cancers." (PMID 19657384, 2009). "With the increasing usage of these agents and the availability of more new agents in the future, knowledge on anti-EGFR therapy is highly relevant to the current state of cancer therapy and to new research directions in the field of oncology." (PMID 19750187, 2009). "Multiple predictive factors to anti-EGFR monoclonal antibodies treatment have been analyzed since this new class of anti-cancer agents have been introduced in the clinical practice and after the role of K-RAS was clarified in this setting." (PMID 19712476, 2009). "Accordingly, the current study showed the importance of EGFR as a candidate for anti-cancer therapy in bladder." (PMID 19243595, 2009). "Mutation of PTEN tumor suppressor gene in human cancer cells leads to activated EGFR downstream signaling including PI3-kinase/AKT and have been linked to resistance to anti-EGFR targeted therapies." (PMID 19878607, 2009). "Targeted therapy has evolved recently as an important treatment modality for cancer, and the most extensively studied pathways for targeted therapy are those related to epidermal growth factor receptor (EGFR)." (PMID 19750187, 2009). "another method is replacing IgG1 with IgG2 like in the cancer medicine Vectibix© (Panitumumab) specific to the EGFR marker (HER1)." (PMID 22649585, 2009). "Epidermal Growth Factor Receptor (EGFR) pathway is one of those biochemical reaction networks believed to play a central role in cancer development." (PMID 19828080, 2009). "Lewis y is mainly distributed at the plasma membrane of cancer cells, and carried by different glycolipids and glycoproteins, such as CD44v6, Muc6 and epidermal growth factor receptor (EGFR), which are related to carcinogenesis." (PMID 20003467, 2009). "The expression of EGFR in several cancer cell lines was determined by Western blotting using antibodies that recognize the N-terminus of mouse EGFR." (PMID 19178753, 2009). "The phosphorylation statuses of two tyrosines on the cytoplasmic tail of EGFR were found to be statistically different, exhibiting greater levels of phosphorylation in cancer." (PMID 19946374, 2009). "Of special interest is a spectrum of EGFR, ABL, MET, FLT3 and KIT cancer mutations that correspond to the same structurally conserved position in the activation loop, which appeared to be mutated in at least 8 different kinases." (PMID 19834613, 2009). "From a theoretical point of view, anti-EGFR cancer treatment requires three parameters to be efficient." (PMID 19367287, 2009). "With a large number of targets per cell, as with many cancer antigens (e.g. EGFR, HER2/neu, CEA), the number of free binding sites exceeds the number of antibodies entering the tissue." (PMID 19956597, 2009). "Our model predicts that the oncogenic EGFR signal passes almost exclusively via the Rap1 pathway and therefore predicts that drugs must target this pathway in order to effectively treat such cancers." (PMID 19804630, 2009). "Understanding the precise role of phosphorylation measurement in regulation of signaling pathways in cancer remains an important challenge, and we primarily focused on the role of EGFR and cell proliferation pathways." (PMID 19946374, 2009). "Owing to its relevance in cancer development, EGFR represents a natural molecular target for a new class of anticancer drugs." (PMID 19293803, 2009). "EGFR is overexpressed and activated in a variety of tumors and provides an attractive target for anti-cancer therapy." (PMID 19657384, 2009). "The EGFR signaling cascade has come under increased attention following observations of increased levels of EGFR gene expression in cancers of the lung, colon, endometrium, and other areas with significant epithelial tissue." (PMID 20028552, 2009).